C3 (complement C3)
Diseases named in the same sentence as C3 in open-access papers (continued):
Sharing a sentence is not in itself a finding about the gene and the disease.
colon carcinoma (13 papers, 2011 to 2025). "In a mouse model of colon carcinoma, C3 is cleaved intracellularly by cathepsin L and B. Tumor-derived C3a triggers the C3a-C3aR-PI3K pathways on TAMs to limit T cell activity." (PMID 38003705, 2023). "The early complement components C3 and C4, and the receptor C5aR have been reported as biomarkers for poor prognosis in gastric and colon cancers, with one mechanism being pro-tumor autocrine actions of C3a and C5a in the TME, including immune infiltration." (PMID 35345676, 2022). "The PPI network showed that CD55 and the key complement system components C3, C4A, and C4B are closely related to colon cancer." (PMID 36741376, 2022). "It has been shown that intracellular C3 in human colon carcinoma Caco2 cells can cleave cathepsin L and B and release C3a, just like CTSL can cleave C3 in CD4+ T cells in a non-C3 convertase manner, and C3a secretion can be downregulated by treatment with cathepsin L and B inhibitors in these cells." (PMID 36969185, 2023). "The effects of BIM and C3 were confirmed in SW480 colon carcinoma cells undergoing Rac-dependent migration on laminin (LN) by mechanisms previously identified to depend functionally on fascin-1-dependent filopodia, dynamic fascin/PKC complexing, and focal adhesion turnover." (PMID 22883572, 2012). "C3+ TeMs (M12) and C1QA+ TeMs (M10) were clustered into the same branch, resembling the IL1B+ macro and C1QC+ TAMs identified in colon cancer, respectively." (PMID 37488416, 2023). "The CXCL family has long been reported as prognostic biomarkers in colon cancer, being involved with inflammatory processes, including genes such as IL-6, C5AR1, and C3 in the IL-6 module." (PMID 31469863, 2019).
leukocytoclastic vasculitis (13 papers, 2008 to 2026). "Skin biopsy demonstrated leukocytoclastic vasculitis with perivascular IgA, IgM, and C3 deposition on direct immunofluorescence, confirming IgA vasculitis." (PMID 42051850, 2026). "Skin biopsy showed leukocytoclastic vasculitis as well as IgA and C3 deposition in the vessel walls." (PMID 39206190, 2024). "A skin biopsy taken from the purpuric eruption showed leukocytoclastic vasculitis with IgA and C3 depositions in the vessel walls of the upper dermis, leading to the diagnosis of IgA vasculitis." (PMID 38577052, 2024). "Skin biopsy typically shows leukocytoclastic vasculitis, with IgA and complement (C3) deposits visible by direct immunofluorescence techniques." (PMID 39518760, 2024). "A skin biopsy showed leukocytoclastic vasculitis with a positive pattern for IgM and C3, as detected through direct immunofluorescence." (PMID 29212535, 2017). "A skin biopsy showed leukocytoclastic vasculitis with IgA and C3 deposition." (PMID 33859912, 2021). "Showing positive immunofluorescence staining for immunoglobulin M (IgM) and complement 3 (C3) in vessel walls without IgA involvement, the skin biopsy results were compatible with leukocytoclastic vasculitis." (PMID 34976803, 2021). "Histopathological analysis of the skin biopsy confirmed leukocytoclastic vasculitis (LCV); however, his DIF was negative for IgG, IgA, IgM, C3, and fibrinogen deposits." (PMID 40376363, 2025).
psoriasis (13 papers, 2015 to 2025). An autoimmune condition characterized by red, well-delineated plaques with silvery scales that are usually on the extensor surfaces and scalp. "Furthermore, using the imiquimod-induced model of psoriasis, it was found that C3 deficient mice showed significantly reduced levels of IL-1β, TNF-α, IL-17a, and IL-23 in the skin and draining lymph nodes and decreased infiltration of neutrophils." (PMID 29713318, 2018). "In the present study, although 5 patients with positive ANA were excluded, low C3 levels were observed in 4 patients, implying that an autoimmune mechanism might play an important role in the association between MN and psoriasis." (PMID 27876003, 2016). "It’s reported C3, and C4 levels were significantly higher in patients with psoriasis than in healthy controls, and the reduction of Bacteroides in psoriasis patients was also found by others." (PMID 33685393, 2021). "Regarding systemic complement activation, sera, and plasma from psoriasis patients showed elevated levels of complement components, complement split products, and regulator proteins including FB, Bb, C3, C3a, C3b, C4, C4a, C4d, C5b-9, C1-INH, C4BP, FH, and FI." (PMID 29713318, 2018). "The pooled serum levels of TNF-α, IFN-γ, IL-2, IL-6, IL-8, IL-18, IL-22, chemerin, lipocalin-2, resistin, sE-selectin, fibrinogen and C3 were higher in psoriasis patients compared with healthy controls (all P < 0.05)." (PMID 29416693, 2018). "Previously, we have found that the percentage of mast cells expressing C3c immunoreactivity is increased in the lesional skin of patients with psoriasis or basal cell carcinoma, and mast cells were suggested to be a marked source for C3 degradation products, including iC3b." (PMID 38310540, 2024). "After activation, C3 is translocated to the dermis, where it stimulates immune cells to produce cytokines, interleukins and growth factors, thereby contributing to the development of psoriasis." (PMID 32731552, 2020). "For instance, S100A8 and S100A9 form a complex called calprotectin that aggravates psoriasis by regulating expression of the C3 complement factor, while hBD-2 promotes chemotaxis of various leukocytes in a C-C chemokine receptor (CCR) 2- and CCR6-dependent manner." (PMID 30918469, 2019). "The present meta-analysis found that TNF-α, IFN-γ, sE-selectin, IL-2, IL-6, IL-8, IL-18, IL-22, fibrinogen and C3 were elevated in serum of patients with psoriasis, indicating that serum levels of these cytokines may correlate to their levels in tissue." (PMID 29416693, 2018). "Treatment of mice with siRNA targeting C3 reduced skin disease in a mouse model of psoriasis." (PMID 29713318, 2018). "In conclusion, serum levels of TNF-α, IFN-γ, IL-2, IL-6, IL-8, IL-18, IL-22, chemerin, lipocalin-2, resistin, sE-selectin, fibrinogen and C3 were significantly elevated and serum level of adiponectin was significantly decreased in psoriasis patients compared to healthy individuals." (PMID 29416693, 2018). "The anaphylatoxin C3a may act as an autocrine stimulus by enhancing C3 synthesis in keratinocytes through its receptor [complement C3a receptor (C3aR)], and it has been detected even in the scales of psoriasis." (PMID 38310540, 2024). "There are no previous studies that investigate the C3-iC3b-CD11b axis in the early phases of psoriasis." (PMID 38310540, 2024). "CTSH was surrounded by CTSS, CTSD and other critical factors involved in complement and adhesion (e.g., C3 and ICAM1) in the psoriasis network, suggesting that it might trigger inflammatory responses by regulating the neighbors in the network." (PMID 30642337, 2019).
bacteremia (12 papers, 2014 to 2025). "Among these, we found up-regulated genes encoding for inflammation and phagocytosis associated proteins (e.g., Apoe, Lgals3, Trem1, and C3), indicating a prolonged transcriptional activation of microglia for at least 20 days following bacterial sepsis." (PMID 37235660, 2023). "This is in agreement with previous findings in experimental pneumococcal meningitis in rabbits depleted of C3 by administering cobra venom with higher bacterial titres in the CSF and C3 deficient mice with increased mortality due to increased bacteremia and systemic complications." (PMID 31883521, 2019). "The C3−/− mice showed remarkably higher levels of bacteremia at all of the tested time points in the first 12 hpi with 106 CFU of Spn6A as compared with WT." (PMID 40073120, 2025). "The activation of classical complement pathways, such as the C3 complement component, is driven by CRP, resulting in opsonisation of pneumococcus and in limiting rapid bacteremia during pneumococcal infection." (PMID 30333823, 2018). "Indeed, a recent prospective study evaluated complement levels in bacteremia patients, and hypothesized the measurement of C3, C4 and C9 levels may help stratify Gram-negative bacteremia patients at increased risk for mortality." (PMID 36261775, 2022).
Cirrhosis (12 papers, 2012 to 2026). A chronic disorder of the liver in which liver tissue becomes scarred and is partially replaced by regenerative nodules and fibrotic tissue resulting in loss of liver function. "The serum concentrations of C3 and C4, as well as the hemolytic activity of the complement, are reduced in patients with decompensated cirrhosis compared to controls; these alterations predispose to infectious processes and confer higher mortality in patients with alcoholic cirrhosis." (PMID 39337069, 2024). "Unlike previous nomograms, besides conventional imaging and pathological variables (i.e., cirrhosis and tumor size, number, resectability and location) our nomogram incorporates serological biomarkers including C3 and PT." (PMID 40052130, 2025). "Investigations identified complement C3, PT, the presence of cirrhosis, tumor capsule, and MVI-M2 as distinct predictors of survival in HCC patients." (PMID 40052130, 2025). "The liver is the synthetic site of complement factors; therefore, low levels of C3 and C4 are seen in patients with cirrhosis." (PMID 38534970, 2024). "Immunoglobin levels (IgM, IgG, and IgA) are decreased in the ascites of patients with cirrhosis, and the concentrations of C3, C4, and CH50 are significantly lower in serum as well as in ascites." (PMID 39337069, 2024). "A fragment of complement C3 increased in cirrhosis and was observed on the 2-DE gel at 38 kDa with an approximate isoelectric point of pI 4.9." (PMID 22761838, 2012). "Opposing the increase in complement C3 seen here, we have previously shown a fragment of C3 decreasing in cirrhosis." (PMID 22761838, 2012). "A fragment of complement C3 was found to be increased in cirrhosis." (PMID 22761838, 2012). "Compared with patients without cryoglobulinemia, the patients with baseline cryoglobulinemia were more frequently female; had higher FIB-4 indexes, IgG and IgM levels; had higher cirrhosis rates; and had lower HCV RNA, TC, eGFR, C3 and C4 levels and platelet counts." (PMID 35371039, 2022). "In autopsy studies, up to 65% of patients with cirrhosis have been reported to show mild IgA deposits in the glomeruli (with or without C3)." (PMID 29634718, 2018).
cryoglobulinemia (12 papers, 2015 to 2025). Cryoglobulinemia is a type of vasculitis that is caused by abnormal proteins (antibodies) in the blood called 'cryoglobulins.' At cold temperatures, these proteins become solid or gel-like, which can block blood vessels and cause a variety of health problems. "In cryoglobulinemia, complement consumption of the C4 component is common, the decrease in both C3 and C4 is more frequent in cryoglobulinemic renal involvement." (PMID 40566113, 2025). "It was observed that cutaneous vasculitis, low C3 and C4 levels, cryoglobulinemia, low CD4 to CD8 ratio, persistent parotid gland enlargement, splenomegaly, and lymphadenopathy are significant risk factors for the development of non-Hodgkin lymphoma." (PMID 36253840, 2022). "Those 6 patients also had no B lymphocyte signs of hyperactivity (hypergammaglobulinemia, rheumatoid factors, low C3 or C4, cryoglobulinemia) except 1 patient, presenting antinuclear antibodies with a titer of 1/640." (PMID 35011983, 2022). "The overall outlook of cryoglobulinemia was reported to be poor in patients with high cryocrit, low C3 values, high creatinine at diagnosis, alveolar haemorrhage, or intestinal ischemia." (PMID 29986657, 2018). "For RPGN, an extensive immunologic screening, looking for ANCA, anti-GBM antibodies, ANA and anti-DNA antibodies, cryoglobulinemia and complements C3 and C4, is needed." (PMID 28474317, 2017). "Six-months after NHL treatment, total ESSDAI score and biological parameters (such as cryoglobulinemia, hypergammaglobulinemia, RF, C3 and C4 levels) were re-assessed." (PMID 25723713, 2015). "Patients with significant systemic activity are generally patients with early onset disease, antinuclear antibodies (ANA) positivity with a higher frequency of anti-Ro/SSA (with or without anti-La/SSB), low C3, low C4 and cryoglobulinemia." (PMID 32698400, 2020). "Laboratory workups for common etiologies of MPGN are frequently negative, including cryoglobulinemia, factors leading to complement alternative pathway dysregulation (C3 nephritic factor, complement factor H antibody) and infectious etiologies." (PMID 29996809, 2018).
Hematuria (12 papers, 2013 to 2025). The presence of blood in the urine. "Univariate linear regression analysis identified uAfamin, 24 hUTP, complement C3, hematuria, and 25(OH)-VD3 as variables significantly associated with rSLEDAI." (PMID 41394867, 2025). "The urinary CFB and C3 are correlated with hematuria, which suggests that CFB and C3 are associated with the activity of IgAN." (PMID 37020564, 2023). "After multivariable logistic regression analysis, age, serum albumin, serum IgA, serum immunoglobulin G, estimated glomerular filtration rate, serum IgA/C3 ratio, and hematuria were found to be independently associated with the presence of IgAN." (PMID 35585099, 2022). "In terms of clinical manifestation, our study unveiled those individuals with IgAN and NS exhibited heightened hematuria and lower C3 levels." (PMID 38439903, 2024). "SLE patients with low C3 levels (<85 mg/dL) and those with hematuria had lower percentages of the three subsets of CD14+PLT+ than patients with normal C3 levels (85–193 mg/dL) and those without hematuria, respectively." (PMID 33947017, 2021). "Clinically, persistent microscopic hematuria and proteinuria, elevated serum IgA level, a high serum IgA/C3 ratio, and macroscopic hematuria with upper respiratory infection are strong indicators of IgAN." (PMID 27095365, 2016). "In the training set, patients in the high-risk group exhibited significantly higher levels of BMI, DBP, neutrophil count, serum creatinine, serum cystatin C, cholesterol, triglycerides, hs-CRP, serum C3, UPE and hematuria compared to those in the low-risk group." (PMID 39494280, 2024).
Hyperglycemia (12 papers, 2009 to 2025). An increased concentration of glucose in the blood. "We found that glomerular C3 protein accumulation suppressed G-Hes supplementation, suggesting that G-Hes exhibits a renoprotective effect through the suppression of complement system activation caused by hyperglycemia." (PMID 39940240, 2025). "Hyperglycemia was associated with lower levels of C1q, C3, and FH but higher serum levels of C3b." (PMID 35370615, 2022). "Thus, hyperglycemic conditions dramatically alter the interaction of C3 and pathogenic bacteria in surprising ways that provide new insight into hyperglycemia-mediated immunocompromise contributing to bacterial infections in diabetic patients." (PMID 22390383, 2012). "The C3-dependent immune response may contribute to destruction of pancreatic islets and hepatic dysfunction, both of which are important risk factors for hyperglycemia." (PMID 29895294, 2018). "Hyperglycemia has been shown to alter the balance of complement activation, reducing levels of C1q and C3 while increasing C3b concentrations." (PMID 40648962, 2025). "Hyperglycemia decreased C4-fragment and C3-fragment opsonization of S. aureus recovered in peritoneal fluids, compared with euglycemic or insulin-rescued rats." (PMID 25610878, 2014). "Hyperglycemia was significantly correlated with elevated C3b or reduced C3, C1q, and FH." (PMID 35370615, 2022). "The expression of Nef protein delivered via HIV-1 vectors in combination with hyperglycemia further augmented the production of ROS, C3, activation of caspase-3, modulation of filamentous protein (F-protein), depolarization of the mitochondria, and loss of astrocytes." (PMID 19878567, 2009).
IgA vasculitis (12 papers, 2020 to 2026). "Stronger staining of C3 than IgA on immunofluorescence and subepithelial humps on electronic microscopy favours the diagnosis of IE over IgA vasculitis." (PMID 35243934, 2022). "Skin biopsy revealed deposition of IgA and C3 complement granular deposition with fibrinogen deposition in superficial dermal vessel walls consistent with IgA vasculitis." (PMID 36176845, 2022). "It was present in biopsies taken both shorter and longer than twenty weeks after the onset of IgA vasculitis, whereas C3 and MBL were present in only the former." (PMID 33643288, 2020). "Some of these skin and kidney biopsies also demonstrated deposition of immunoglobulin A and complement C3, with some authors arguing for, and some against, the diagnosis of Henoch-Schönlein purpura, which clinically presents with purpura, abdominal pain, and lower extremity arthralgias." (PMID 39087182, 2024).
Sjögren’s syndrome (12 papers, 2012 to 2025). "A recent analysis of serologic evidence with a meta-analysis of the association of EBV and Sjögren’s syndrome revealed an inverse association between the titer of anti-EA IgG and C3 and C4 levels." (PMID 37047126, 2023). "Notably, mutations in the genes encoding C2, C3, C4A, C4B have been linked to SLE, and Sjogren’s syndrome has been reported in patients with genetic deficiencies in C1q, C4, and C2." (PMID 32514272, 2020). "We further analyzed the correlation of titer of anti-MDM2 and European Sjogren's syndrome disease activity index (ESSDAI), complement 3 (C3), complement 4 (C4), immunoglobulin and other laboratory findings including level of platelet (PLT), hemoglobin (HB) and white blood cell count (WBC)." (PMID 28147328, 2017).
type 1 diabetes (12 papers, 2006 to 2025). "C3 has also proved to be higher in young adults with type 1 diabetes and a decrease in HbA1c in this group has been associated with a decrease in C3 levels." (PMID 25415563, 2014). "SNPs within the complement genes may contribute to IA, the first step to type 1 diabetes, with at least one SNP in C3 significantly associated with clinically diagnosed type 1 diabetes." (PMID 27306948, 2016). "Our study on young onset type 1 diabetes population was the first study of C3 N-glycosylation changes in any disease, and the results confirmed the relevance of C3 N-glycome analysis." (PMID 37293493, 2023). "Particularly, C3 contributes to the development of type 1 diabetes by enhancing the organ-specific autoimmune inflammatory processes." (PMID 37293493, 2023). "We demonstrated that C3 N-glycan profile is stable in a healthy individual, and results showed that C3 N-glycosylation profile is significantly changed in type 1 diabetes." (PMID 36031042, 2022). "This could possibly be explained by endoplasmic reticulum (ER) stress typical for renal and pancreatic cells in type 1 diabetes, and the fact that kidneys and pancreatic islets also highly express C3, contributing to its total production with about 4% each." (PMID 37293493, 2023). "•Significant changes of C3 N-glycosylation accompanying the onset of type 1 diabetes." (PMID 36031042, 2022). "An infection could precipitate type 1 diabetes in those with genetic predisposition (based upon rs2230199 in C3) since the expression levels of C3 could be different and these subject would not be able to vigorously fight the pathogen." (PMID 27306948, 2016). "Also, the gene encoding the main protein of the complement activation pathway, complement C3 protein, has been associated with an increased risk of type 1 diabetes development among HLA-DR4/4 carriers, further demonstrating an important role of the complement system in type 1 diabetes." (PMID 35622127, 2022). "Kininogen/complement C3/complement C4-A were not correlated with maternal HbA1c in all three trimesters in women with type 1 diabetes." (PMID 35610262, 2022).